BCL2A1 (BCL2 related protein A1)
Diseases named in the same sentence as BCL2A1 in open-access papers (continued):
Sharing a sentence is not in itself a finding about the gene and the disease.
infection (20 papers, 2008 to 2025). The state of being infected such as from the introduction of a foreign agent such as serum, vaccine, antigenic substance or organism. "As for some DZ signature genes, the LZ biomarker CD83 is downregulated upon infection in ensemble experiments but retained in EBV+ subsets co-expressing BCL2A1 (BFL-1) and other GC LZ hallmarks (CD80, CD86, and MYC)." (PMID 38059622, 2024). "Similar to the results of inhibiting miR-3976, transfection with pcDNA3.1-BCL2A1 reduced the percentage of apoptotic cells, while knockdown of BCL2A1 with siRNA increased the apoptosis rate of HCT-8 cells after infection." (PMID 37415254, 2023). "A majority (64/92) of NF-κB signaling pathway genes were downregulated more than 2-fold with infection, whereas only 5 of 92 were upregulated, BCL2A1, IL1B, CXCL8, MMP9, and SOD2." (PMID 33194960, 2020). "Downregulation of BCL2A1 mRNA led to a strong growth retardation of almost 60% after two days of infection when compared to control cells." (PMID 23741337, 2013). "Additionally, there is downregulation in the expression of apoptosis inhibiting genes like NAIP and BCL2A1 following infection." (PMID 39287214, 2024). "Because NF-κB is also an early response signal after infection and stress, it is of interest to investigate whether the induction of BCL2A1 is mediated by NF-κB signaling after hypoxia treatment." (PMID 34572804, 2021). "Therefore, increased abundance of two Bcl-2 family members (MCL1 and BCL2A1) at an early time post-infection in THP-1 macrophages by R. conorii may be a strategy to promote host cell survival and retain a replicative niche." (PMID 31024862, 2019). "In addition, another BCL-2 family member, BCL2-related protein A1, was also significantly up-regulated in HBMs (>8-fold), which suggested that HBMs may antagonize cell apoptosis during the early stage of infection." (PMID 24130911, 2013). "The balanced upregulation of pro-apoptotic (FAS, BBC3) and anti-apoptotic (BCL2A1, TRAF1) genes in TIGR4-infected cells likely mitigates extensive cell death, enabling Spn to maintain host cell viability for sustained infection." (PMID 40475528, 2025). "Transcripts of caspase 3 (CASP3), Acyl coenzyme A-binding protein (DBI), death inducer-obliterator-1 (DIDO1) and Bcl2-related protein A1 (BCL2A1), are pro-apoptotic proteins or induced by apoptosis, and were down-modulated upon infection." (PMID 18495030, 2008). "Infection by H. pylori led to a striking albeit transient up-regulation of BIRC2, BIRC3 and BCL2A1." (PMID 35089437, 2022).
hematological malignancies (5 papers, 2017 to 2024). "In addition, BCL2A1 was a critical mediator of B‐cell survive and regulated by Spleen tyrosine kinase and Bruton tyrosine kinase, and was associated with advancement of hematological malignancies as well as solid tumor." (PMID 35603962, 2022). "Therefore, selective BCL2 inhibitors, such as venetoclax, which has been shown to be effective against hematological malignancies 45, might be an option for targeted treatment, particularly for patients with BCL2A1-positive PSCC." (PMID 33391539, 2021).
immune dysfunction (1 paper, 2022). "In addition, over-expression of BCL2A1 on neutrophils might be correlated to delayed neutrophil apoptosis and can lead to immune dysfunction and persistent inflammation." (PMID 35832273, 2022).
BCL2A1 also shares sentences with these, for which no sentence is quoted: colon cancer (4 papers); blood cancer (3); stomach cancer (3); acute lymphoblastic leukemia (2); autoimmune disease (2); cardiovascular diseases (2); Hyperglycemia (2); skin squamous cell carcinoma (2); Wilms tumor (2); allergic disease (1); asthma (1); atopic dermatitis (1); bipolar disorder (1); bladder cancer (1); brain cancer (1); Burkitt lymphoma (1); carcinoid (1); cardioembolic stroke (1); chronic kidney disease (1); chronic myeloid leukemia (1); Ewing sarcoma (1); experimental autoimmune encephalomyelitis (1); Hodgkins lymphoma (1); Hypertension (1); infectious disease (1); Insulin resistance (1); Langerhans cell histiocytosis (1); latent infection (1); lung squamous cell carcinoma (1); lymphoid tumour (1).
A further 18 diseases each share a sentence with BCL2A1 in 1 paper.